STAT3 (signal transducer and activator of transcription 3)
Diseases named in the same sentence as STAT3 in open-access papers (continued):
Sharing a sentence is not in itself a finding about the gene and the disease.
osteosarcoma (continued). "However, overexpression of miR-483 could downregulate STAT3 expression, thereby inhibiting the metastasis and invasion of osteosarcoma cells." (PMID 33546665, 2021). "Therefore, our work provided a promising strategy that diosmetin may be used in clinic practice for the treatment of osteosarcoma and revealed that STAT3 might be a promising therapeutic target for osteosarcoma." (PMID 34922636, 2021). "Diosmetin markedly inhibited the proliferation ability of osteosarcoma cells, while IL-6 administration, which could simulate STAT3 signaling activation, counteracted diosmetin-induced anti-osteosarcoma effect and significantly, although partly, reverse proliferation of Saos-2 or U2OS cells." (PMID 34922636, 2021). "Apatinib inhibited osteosarcoma growth in vitro by inducing autophagy and apoptosis of osteosarcoma cells via directly inhibiting expression of the antiapoptotic protein Bcl-2 and inactivating signal transducer and activator of transcription 3 (STAT3), which is mediated by VEGFR248." (PMID 30816108, 2019). "Collectively, the results of this study demonstrated that BD exerts a strong inhibitory effect on tumor growth and stem cell like traits of osteosarcoma which may be partially due to STAT3 inhibition, suggesting that BD maybe a promising therapeutic candidate against osteosarcoma." (PMID 31631559, 2019). "Thus, our work, which reveals that NP blocks STAT3-dependent tumor progression and metastasis of osteosarcoma, could be useful in targeting osteosarcoma." (PMID 30286779, 2018). "Thus, given the apparent role of the eIF4E pathway in malignant transformation, it is possible that NP-induced STAT3-dependent control of osteosarcoma cell functions could, in part, work through the regulation of protein synthesis." (PMID 30286779, 2018). "Moreover, STAT3 inhibition plays a role in osteosarcoma cell proliferation, survival and migration." (PMID 28423603, 2017). "Therefore, ADSC-induced STAT3 activation in OS cells may play a central role in the penetration of osteosarcoma into neighbouring soft tissue." (PMID 28423603, 2017). "Therefore, we hypothesized that AMBN functions as a tumor suppressor in osteosarcoma through the inhibition of Src and its downstream Stat3 activities." (PMID 28054649, 2017). "Finally, STAT3 is involved in drug resistance in osteosarcoma cell lines." (PMID 25146150, 2014). "Our results suggest that ERK1 and STAT3 expression are good predictive markers for chemotherapy response and that inhibitors might be used in combination with common chemotherapeutic drugs in conventional osteosarcomas." (PMID 25146150, 2014). "However, whether constitutive Stat3 signaling plays a role in the survival and growth of osteosarcomas, rhabdomyosarcomas, and soft-tissue sarcomas is still unclear." (PMID 17598902, 2007). "We found that DUSP3 affected osteosarcoma proliferation, migration, and invasion by regulating the Epidermal Growth Factor Receptor (EGFR)/STAT3/SOX2 axis." (PMID 39744427, 2025). "Our results showed that DUSP3 binds to EGFR, inhibiting its phosphorylation, thereby regulating STAT3/SOX2 axis and affecting osteosarcoma cell stemness." (PMID 39744427, 2025). "In osteosarcoma, DLGAP5 has been demonstrated to promote tumor development via the IL-6/JAK2/STAT3 signaling pathway." (PMID 40181976, 2025). "LncRNA NEAT1 also enhances STAT3-induced EMT and metastasis in osteosarcoma through the miR-483/STAT3 axis." (PMID 39937018, 2025). "Through modulating the EGFR/STAT3/SOX2 axis, DUSP3 restrains osteosarcoma cell growth, migration, invasion, and stemness." (PMID 39744427, 2025). "In osteosarcoma, PL modulates the Janus kinase/signal transducer and activator of transcription 3 (JAK/STAT3) signaling pathway via miR-30d-5p." (PMID 41226811, 2025). "Network pharmacology showed that 251 luteolin against osteosarcoma targets and 8 hub targets including AKT1, ALB, CASP3, IL6, JUN, STAT3, TNF, and VEGFA." (PMID 40066267, 2025).
osteosarcoma (continued). "DUSP3 impairs osteosarcoma cells proliferation, migration, invasion, and stemness through regulating the EGFR/STAT3/SOX2 axis." (PMID 39744427, 2025). "In conjunction with our earlier in vitro research, we can infer that DUSP3 inhibits osteosarcoma development and lung metastasis in vivo through regulating EGFR/STAT3/SOX2 axis." (PMID 39744427, 2025). "After the addition of the STAT3 inhibitor BP-1-102, the expression levels of Nrf2 and GPX4 in cisplatin-resistant osteosarcoma cells were significantly reduced." (PMID 38469234, 2024). "In addition, the experimental results showed that overexpression of miR-506-3p reduced the STAT3 protein expression level in doxorubicin-resistant osteosarcoma cells U-2OS/Dox, indicating that miR-506-3p could inhibit the expression of STAT3 in osteosarcoma cells." (PMID 38420199, 2024). "In osteosarcoma, MET has been shown to regulate osteosarcoma progression by mediating the activity of the STAT3/Akt pathway." (PMID 38468814, 2024). "This study aims to determine the correlation between immunoexpression of STAT3, IL6, and EGFR and immunoexpression of PD-L1 in osteosarcoma patients, while also evaluating their expressions in pediatric and nonpediatric patients." (PMID 38434518, 2024). "Research has confirmed that miR-506-3p can counteract chemoresistance to doxorubicin in U-2OS osteosarcoma cells by inhibiting JAK2 phosphorylation and lowering total STAT3 protein levels in drug-resistant cells." (PMID 39679367, 2024). "In our study, these results indicated that FANCD2 silencing inhibited osteosarcoma cells and tumor growth, as well as promoted ferroptosis by activating JAK2/STAT3 pathway." (PMID 36814203, 2023). "Exosomes have been shown to regulate the development of osteosarcoma as part of drug delivery, and can positively affect osteosarcoma through signaling pathways such as Wnt/β-catenin, ERK1/2, and JAK2/STAT3." (PMID 36678850, 2023). "For instance, bavachin induces ferroptosis in osteosarcoma cells by down-regulating STAT3 and GPX4, and increasing intracellular Fe2+ levels, thereby exerting anti-tumor effects on osteosarcoma." (PMID 36814203, 2023). "Ferroptosis is involved tumor drug resistance by impairing STAT3/Nrf2/GPX4 signaling, and it increases the sensitivity of osteosarcoma cells to cisplatin." (PMID 36899330, 2023). "It has been shown that DLGAP5 can activate interleukin-6/Janus kinase 2/signal transducer and activator of transcription 3 (IL-6/JAK2/STAT3) signaling pathway thereby promoting the proliferation and invasion of osteosarcoma cells." (PMID 36712920, 2023). "Acute high glucose exposure promoted XRCC1 expression through STAT3 activation, increasing the repair of methyl methanesulfonate-induced DNA damage in HEK293T cells and the osteosarcoma cell line U2OS." (PMID 35457130, 2022). "In this study, we showed that TIPE1 inhibits STAT3 transactivation and expression via PRMT1, resulting in decreased osteosarcoma tumorigenesis and progression." (PMID 36151091, 2022). "For illustration, it was found that inhibition of STAT3/Nrf2/GPX4 signaling induced ferroptosis sensitization, thereby enhancing the sensitivity of osteosarcoma cells to cisplatin." (PMID 35837104, 2022).
osteosarcoma (continued). "We selected the osteosarcoma cell line U2OS, which has high STAT3 activation, and HEK293T, which we showed previously has an inducible STAT3 response." (PMID 35457130, 2022). "Thus, we speculated that miR-483 might participate in the regulation of osteosarcoma through STAT3." (PMID 33546665, 2021). "Closing the feedback circuit between MSCs and bone sarcoma cells, several works have identified STAT3 as the main pro-stemness and pro-tumorigenic factor induced by MSC-released IL-6 in osteosarcoma cells." (PMID 34198693, 2021). "Although our study is not the first study reporting the association between NEAT1 and miR-483, it describes the regulation of STAT3 by miR-483 and their functions in regulating the EMT and metastasis of osteosarcoma cells for the first time." (PMID 33546665, 2021). "In osteosarcoma, FLLL32 treatment decreased p-STAT3 and total STAT3 expression, as well as promoted caspase-3-dependent apoptosis." (PMID 34769290, 2021). "Treatment of osteosarcoma cells with FLLL32 decreased the expression of survivin, VEGF, and MMP2 at both mRNA and protein levels with a concomitant decrease in STAT3 levels." (PMID 34671398, 2021). "RNA-Seq of KDM5A-KO cells indicated that interferon, epithelial–mesenchymal transition (EMT), IL6/JAK/STAT3, and TNF-α/NF-κB pathway were likely involved in the regulation of osteosarcoma cell viability." (PMID 33436536, 2021). "In osteosarcoma cell Saos-2 cells, ORV inhibited cell viability and induced apoptosis by suppressing the activation of STAT3 (signal transducer and activator of transcription 3)." (PMID 34299485, 2021). "HOTAIR was overexpressed in cisplatin (DDP)-resistant osteosarcoma cells and tissues and enhanced DDP resistance of osteosarcoma cells through the miR-106a-5p/STAT3 axis." (PMID 34367966, 2021). "It has been suggested that, in osteosarcoma, miR-19a inhibits the JAK2/STAT3 signaling pathway, activates the mitochondrial apoptotic pathway, and promotes the expression of apoptosis-related proteins." (PMID 33504017, 2021). "In conclusion, ML264 inhibits osteosarcoma growth and metastasis by inhibiting the JAK2/STAT3 and Wnt signalling pathways." (PMID 32285603, 2020). "In this study, we reveal that STAT3 knockdown attenuates the expression of PD-L2, p-LIMK2 and p-cofilin in osteosarcoma, suggesting that VEGFR2 inhibition suppresses migration, invasion and PD-L2 expression by targeting the STAT3 and RhoA-ROCK-LIMK2 pathways." (PMID 33014879, 2020). "IL-6 appears to promote the proliferation, metastasis and angiogenesis of osteosarcoma through several downstream signals including AKT, ERK1/2 MAPK and STAT3." (PMID 32257109, 2020). "Cucurbitacin I suppressed STAT3 phosphorylation, downregulating STAT3 targets Mcl-1, c-Myc, cyclin D1 and survivin and upregulating the cleavage of PARP proteins in vitro and in vivo models of osteosarcoma." (PMID 32731620, 2020). "In conclusion, ML264 inhibited the JAK2/STAT3 and Wnt/β‐catenin signalling pathways via down‐regulation of KLF5 and EGR1 expression, thereby inhibiting proliferation and metastasis of osteosarcoma cells." (PMID 32285603, 2020). "TAMs facilitated the expression of cyclooxygenase 2 (COX-2) of osteosarcoma cells and activate the COX-2/STAT3 axis and epithelial-mesenchymal transition (EMT) to promote osteosarcoma invasion and lung metastasis." (PMID 33363016, 2020). "Mechanistically, the inhibitory role of BD on osteosarcoma cell growth and migration including OSC stemness was partially executed through the inhibition of STAT3 signaling pathway." (PMID 31631559, 2019). "The effect of STAT3 and EGFR co-inhibition on osteosarcoma cell viability was evaluated by calculating drug combination index (CI) values using the MTT assay." (PMID 31422383, 2019). "Western blotting was carried out to determine the expression of total and phosphorylated STAT3 and EGFR levels in osteosarcoma cells after combined treatment with SC and erlotinib." (PMID 31422383, 2019).
osteosarcoma (continued). "To further study the effect of NP on STAT3 activation in osteosarcoma cells, we determined its effect on IFN-γ–dependent regulation and activation of STAT3." (PMID 30286779, 2018). "Our results demonstrated that resveratrol inhibited osteosarcoma cell proliferation and tumorigenesis ability, which was correlated with cytokines inhibition related JAK2/STAT3 signaling blockage." (PMID 30356255, 2018). "In osteosarcoma, Parkin is often downregulated, and this leads to activation of the JAK/STAT3 pathway." (PMID 30341316, 2018). "Western blot analysis showed that NP treatment blocks IFN-γ–activated induction of STAT3 expression in both 143B and MG63 osteosarcoma cells." (PMID 30286779, 2018). "Simvastatin was shown to suppress phosphorylation of JAK2 and STAT3 in two human renal cell carcinoma cell lines in a nude mouse model and growth hormone-stimulated JAK2 and STAT5 activation in osteosarcoma cells." (PMID 30116531, 2018). "As a result, CD63 was ubiquitously expressed among human osteosarcoma cell lines, and CD63 knockdown reactivated Stat3 in AMBN-inducible 143B-Luc cells." (PMID 28054649, 2017). "Apatinib repressed the expression of STAT3 and BCL-2 and suppressed the growth of osteosarcoma in vivo." (PMID 28837148, 2017). "In renal cell carcinoma and osteosarcoma, ginkgetin induced cell apoptosis through JAK2/STAT3 signaling." (PMID 29190983, 2017). "We established tibia osteosarcoma models in nude mice using human OS MG63 cells to determine the contributions of ADSCs and STAT3 to osteosarcoma growth and metastasis in vivo." (PMID 28423603, 2017). "4-MD inhibited phosphorylation of JAK2 and STAT3 with the inactivation of mitogen-activated protein kinases (MAPKs) and CREB, and the upregulation of PTEN in osteosarcoma cells." (PMID 26755649, 2016). "In contrast, oncostatin M promotes STAT3 activation, VEGF production, and invasion in osteosarcoma cell lines." (PMID 25146150, 2014). "Our current work shows that at concentrations of drug that abrogate STAT3 phosphorylation, LLL12 blocks angiogenesis, and suppresses tumor vasculature in osteosarcoma tumors." (PMID 22530037, 2012). "To evaluate the expression and activation of Stat3 pathway, we analyzed the protein expression in several pairs of both drug sensitive and MDR osteosarcoma cell lines and 8 samples of osteosarcoma tissues." (PMID 20459702, 2010). "Our results demonstrated that Stat3 pathways were constantly activated in osteosarcoma and MDR osteosarcoma cells." (PMID 20459702, 2010). "In this study, we observed that elevated levels of Stat3 and pStat3 are detected in osteosarcoma drug sensitive cell lines KHOS, U-2OS, SaOS and osteosarcoma MDR cell lines KHOSR2, U-2OSTR." (PMID 20459702, 2010). "Expression of Stat3, phosphorylated Stat3 (pStat3) and Stat3 targeted proteins, including Bcl-XL, Survivin and MCL-1 were determined in drug sensitive and MDR osteosarcoma cell lines and tissues by Western blot analysis." (PMID 20459702, 2010). "To examine whether Stat3 is activated in osteosarcomas, rhabdomyosarcomas and other soft-tissue sarcomas we analyzed sarcoma tissue microarray slides and sarcoma cell lines using immunohistochemistry and Western blot analysis, respectively, with a phospho-specific Stat3 antibody." (PMID 17598902, 2007). "Transcriptome sequencing revealed that DUSP3 expression level was closely related to the STAT3/SOX2 signaling pathway, which may be the specific mechanism by which DUSP3 restrains the malignant behaviors of osteosarcoma." (PMID 39744427, 2025). "While activation of STAT3 is tightly regulated in non-malignant cells, it is persistently activated in most hematologic malignancies and solid cancers, including osteosarcoma." (PMID 40529368, 2025). "STAT3 regulates the transcriptional activation of several anti-apoptotic and pro-proliferative genes, such as BCL-2, so attenuation of STAT3 phosphorylation can promote apoptosis in human osteosarcoma." (PMID 39860065, 2025).
osteosarcoma (continued). "This study revealed the correlation between PD-L1, STAT3, and EGFR, which may indicate the role of STAT3 and EGFR in PD-L1 regulation in osteosarcoma." (PMID 38434518, 2024). "Similarly, TAMs promote migration and invasion of osteosarcoma cells and induce EMT via the STAT3 pathway by upregulating COX-2 and MMP9." (PMID 39068459, 2024). "So far, the role of miR-506-3p reversing doxorubicin resistance by regulating STAT3 in osteosarcoma has not been reported." (PMID 38420199, 2024). "This may become the basis of further research targeting STAT3 and EGFR in addition to PD-1/PD-L1 immunotherapy in osteosarcoma." (PMID 38434518, 2024). "The existence of a correlation between PD-L1, STAT3, and EGFR indicates the potential role of STAT3 and EGFR in PD-L1 regulation in osteosarcoma, which may become the basis for targeted therapy." (PMID 38434518, 2024). "Meanwhile, the reduction of STAT3 and GPX4 leads to increased ferroptosis in osteosarcoma cells." (PMID 36814203, 2023). "It has been reported that lymphocyte cytoplasmic protein 1 (LCP1) in BMSC-Exos promotes the progression of osteosarcoma through the JAK2/STAT3 pathway, suggesting that targeting LCP1 may provide a means to treat osteosarcoma." (PMID 36678850, 2023). "Besides these, we found KLF4, STAT3, BCL6, TFAP2A, and TFAP4 as potential drivers of osteosarcoma metastasis." (PMID 37938582, 2023). "This study shows that luteolin may regulate multiple signaling pathways by targeting various genes like AKT1, STAT3, IL6, TNF, and VEGFA to inhibit osteosarcoma proliferation and metastasis." (PMID 37749554, 2023). "Drugs targeting transcription factors (e.g., STAT-3 and STAT5) controlling the development of CSCs may also be used to improve the therapeutic approaches to osteosarcoma." (PMID 35582537, 2022). "However, when BP-1-102, a STAT3 inhibitor, was used, the expression levels of NRF2 and GPX4 were strikingly decreased, which reactivated ferroptosis and enhanced the sensitivity of osteosarcoma cells to cisplatin." (PMID 36557902, 2022). "Induction of each of the DUBs in BJhTERT fibroblasts and U2OS osteosarcoma cells led to prolonged and/or shifted activation of STAT3 in response to PDGF-BB stimulation, which in turn led to increased transcriptional activity of STAT3." (PMID 35064336, 2022). "The influence of cell effects is supported by studies that describe paracrine interactions between MSCs and osteosarcoma cells driving resistance to doxorubicin, whereby MSC-secreted IL-6 protects tumour cells by STAT3 activation from doxorubicin-induced apoptosis in vitro and in vivo." (PMID 34638373, 2021). "Therefore, diosmetin, to some extent, exerts anti-osteosarcoma effects partly via signaling pathways (such as Wnt and RANKL/RANK), in addition to dramatically inhibiting the activation of STAT3/c-Myc signaling pathway." (PMID 34922636, 2021). "In this study, we demonstrated that the administration of diosmetin on osteosarcoma cells like Saos-2 and U2SO cells significantly inhibited cell proliferation while promoted apoptosis, with remarkable reduction of STAT3, p-STAT3 and its downstream protein c-Myc levels in a dose-dependent manner." (PMID 34922636, 2021). "In osteosarcoma cells, IL-6 produced by MSCs activates the JAK2/STAT3 signaling, with the subsequent up-regulation of multidrug resistance protein (MRP) and P-gP expression, which is relevant to poor response rates of clinical osteosarcoma chemotherapy." (PMID 34095111, 2021). "However, NEAT1 sponged miR-438, increased STAT3 expression, and repressed STAT1 expression, subsequently increasing the EMT of osteosarcoma cells." (PMID 33546665, 2021). "Furthermore, induction of JAK2/STAT3 axis by exosomal LCP1 leads to carcinogenesis and migration of osteosarcoma cells." (PMID 34769099, 2021).